IL10 (interleukin 10)
Diseases named in the same sentence as IL10 in open-access papers (continued):
Sharing a sentence is not in itself a finding about the gene and the disease.
endometriosis (continued). "CD8 expression on iNKT cells in combination with the regulatory cytokines IL-6, IL-17 and IL-10 were unaltered between health and endometriosis controls." (PMID 37497226, 2023). "In the present study, IL-6, IL-8, IL-10, IL-18, IL-23, IFN-α2 and MCP-1, which are associated with endometriosis and considered to be exacerbating factors in endometriosis, were significantly lower in the treated group." (PMID 37629072, 2023). "Accumulating evidence has demonstrated that IL-10 is sharply increased in the ectopic endometrium and peritoneal fluid of female people with endometriosis, particularly in cases of advanced endometriosis." (PMID 37600687, 2023). "It was concluded that the interaction between ESCs and macrophages impairs the cytotoxicity of NK cells in endometriosis by secreting IL-10 and TGF-β." (PMID 36865552, 2023). "T helper 17 (Th17) cells, which produce IL-17 and IL-10, are increased in the peritoneal fluid of patients with endometriosis and promote angiogenesis and inflammation." (PMID 37834449, 2023). "proved that IL-27, secreted by macrophages and ESCs, induces Th17 cells to produce IL-10 via a c-Maf/RORγt/Blimp-1 signal, promoting the development of endometriosis." (PMID 36865552, 2023). "High levels of IL-10 in endometriosis play a significant role by decreasing the activity of CD4+ T-cells in the peritoneal fluid of affected patients." (PMID 37834449, 2023). "Expression of cytokines IL-2, IL-6, IL-10, and IL-15 was lower in endometriosis lesions than in eutopic endometrium in the secretory phase." (PMID 35269619, 2022). "And IL-27 was considered to induce the IL-10 and IL-17A double-producing Th17 cells in endometriosis." (PMID 35582411, 2022). "The presence of higher values of IL-4 and IL-10 in the peritoneal fluid confirms that the development of endometriosis is accompanied by the activation of a Th2-type immune response at the local level." (PMID 35805112, 2022). "IL-10 levels were significantly higher in the PM in endometriosis patients, and a similar trend was seen in PBMC." (PMID 35565370, 2022). "But some of them still found IL-17/IL-10 and IL-17/IL-23 ratios were respectively increased in PF and serum samples from endometriosis group." (PMID 35582411, 2022). "The endometriosis related peritoneal macrophages towards to M2-type, manifested by hypersecretion of IL-10 and decreased phagocytosis, and the increase of CD163." (PMID 36263059, 2022). "In this way, increased levels of TNF-α, IL-6, IL-8, IL-10, VEGF, and MCP-1/CCL2, as well as different metalloproteinases (MMPs), are associated with the establishment and progression of endometriosis." (PMID 35164046, 2022). "Studies on a mouse model of surgically induced endometriosis allowed the authors to conclude that the growth of ectopic endometrium is promoted with a corresponding change in IL-10 concentration." (PMID 35805112, 2022). "Even if the involvement of the IL-10 pathway in endometriosis is still poorly understood, the IL-10 signaling pathway has an ability to block cytokines and chemokines from macrophages being the root of inflammatory processes." (PMID 36120440, 2022). "FKN, a chemokine involved in the adhesion and migration of immune cells, alters cytokine production with upregulation of IL‐10 and downregulation of IL‐12, implicating a protective effect of macrophage against endometriosis progression." (PMID 36310658, 2022). "In a 2021 study, the measurement of IL-10 in follicular fluid was able to perfectly differentiate between endometriosis patients and controls." (PMID 35620300, 2022). "It was postulated that IL-10 suppresses immunity against endometrial implants that contribute to the development of endometriosis." (PMID 36555618, 2022). "There is also an increase in the proinflammatory and anti-inflammatory cytokines IL-1, IL-4, IL-6, IL-8, IL-10 and TNFα in the serum and in peritoneal fluid of women with endometriosis, particularly in advanced stages." (PMID 35888644, 2022).
endometriosis (continued). "The strong induction of HO-1 and IL-10 in peritoneum in endometriosis patients indicate M2-like skewing of macrophages." (PMID 35565370, 2022). "Conversely, the concentration of IL-12, an anti-inflammatory cytokine, inflammatory cytokine IL-10 and E-cadherin levels were lower among endometriosis patients compared to controls." (PMID 35620300, 2022). "Shifts towards the Th2 immune response have been found to be involved in endometriosis, with a relative predominance of IL-4 and IL-10." (PMID 34289871, 2021). "The administration of the vaccine before the induction of endometriosis prevented the increase of Th-2 dependent cytokines: IL4, IL6, and IL-10, which is typically observed during the development of endometriosis." (PMID 34945174, 2021). "We further demonstrated that the IL-10–IL-10 receptor axis promotes angiogenesis in vitro and in vivo and promotes endometriosis pathogenesis during the early stage of disease." (PMID 33807420, 2021). "Some evidence demonstrated that anti-inflammatory cytokines, in particular IL-10, are sharply increased in peritoneal fluid and the ectopic endometrium of women with endometriosis." (PMID 34064310, 2021). "On the other hand, it has been reported that there is an increase in the levels of the anti-inflammatory cytokine IL-10 in the peritoneal cavity of patients with endometriosis." (PMID 34639133, 2021). "This study explored the cellular source and angiogenic activity of local IL‐10 during the early stage of endometriosis." (PMID 31418859, 2019). "Next, we explored the effect of IL‐10 on angiogenesis in the lesions, as angiogenesis is a key step for lesion survival and growth during the early stage of endometriosis development." (PMID 31418859, 2019). "IL-10 in serum and peritoneal fluid from patients with endometriosis has shown significantly increased levels in contrast to those from healthy women." (PMID 32063886, 2019). "Taken together, these results show that IL‐10 secreted from local plasmacytoid dendritic cells promotes endometriosis development through pathological angiogenesis during the early disease stage." (PMID 31418859, 2019). "On the other hand, neutralization of IL-6 with antibody decreased the expression of CD163 and IL-10 in macrophages in an endometriosis condition, reflecting prevention of macrophage polarization toward an M2 phenotype." (PMID 30276219, 2018). "These IL-10 and IL-17A double-producing Th17 cells promote the growth, adhesion, invasion and deep infiltration of ESCs, thus accelerating the progression of endometriosis." (PMID 28300844, 2017). "IL-10+Th17 cells, in turn, stimulate the proliferation and implantation of ectopic lesions and accelerate the progression of endometriosis." (PMID 28300844, 2017). "Here, we report that IL-10+Th17 cells are significantly increased in the peritoneal fluid of women with endometriosis, along with an elevation of IL-27, IL-6 and TGF-β." (PMID 28300844, 2017). "In advanced endometriosis, the formation of a c-Maf, RORγt and Blimp-1 complex triggered by IL-27 contributes to the expansion of IL-10-producing Th17 cells." (PMID 28300844, 2017). "The present study investigated the differentiation mechanism and role of IL-10-producing Th17 cells in endometriosis." (PMID 28300844, 2017). "Ho and colleagues found increased levels of IL-10 in the PF of women with endometriosis compared to normal women." (PMID 26247027, 2015). "A more recent study by Suen and colleagues showed that serum levels of IL-10 were higher in endometriosis patients compared to both healthy subjects and subjects with other gynecological diseases." (PMID 26247027, 2015). "Collectively, these results suggest that TECK promotes Treg differentiation in the endometriotic milieu and that the Tregs, in turn, stimulate the development of endometriosis through IL-10, TGF-β and CD73." (PMID 25275597, 2014).
endometriosis (continued). "A mouse model of surgically induced endometriosis demonstrated that IL-10 promoted the growth of endometriosis lesions and this was suggested to be due to IL-10 supressed immunity allowing endometrial implants to develop." (PMID 25207642, 2014). "Only one gene, IL10, was significantly increased at the sites prone to endometriosis when compared control peritoneal (fold change 2.75, p = 0.026)." (PMID 25207642, 2014). "According to Wu and Ho, IL-10 is produced in increased amounts by activated macrophages in peritoneal fluid of patients with endometriosis." (PMID 24298555, 2013). "Additionally, B cells can suppress inflammatory immune responses and promote endometrial cell proliferation in endometriosis by secreting IL-10 and IL-35." (PMID 40679648, 2025). "Furthermore, it has been found that “G” allele of IL-10 rs1800896 (G/A at position −1082) SNP is associated with increased susceptibility to both SLE and endometriosis." (PMID 40725086, 2025). "Besides proinflammatory cytokines, endometriosis patients show elevated levels of immunoregulatory cytokines IL-10 and TGF-β." (PMID 41488658, 2025). "In endometriosis, IL-10 secreted from plasmacytoid dendritic cells could also promote angiogenesis in the early stage." (PMID 38459564, 2024). "IL-10, though typically anti-inflammatory, may alter immune responses in ways that support chronic inflammation in endometriosis." (PMID 39796020, 2024). "Additionally, studies have demonstrated that the immune factor IL-27 in endometriosis accelerates the development of endometriosis by triggering the production of IL-10 by Th17 and promoting the proliferation and implantation of ectopic lesions." (PMID 38627726, 2024). "IL-10 may contribute to the dysregulation of the immune response observed in patients with endometriosis, by modulating local inflammation and contributing to remove apoptotic cells then reducing the local inflammatory response." (PMID 39595086, 2024). "IL-10 follows the same pattern both serologically and tissue-wise as IL-8, with non-significantly different serum levels between the two study groups but significantly different tissue levels between them, showing higher expression in endometriosis." (PMID 39202309, 2024). "According to the hypothesis, stimulation of macrophages in patients with endometriosis may be a result of IL-10, which is augmented within earlier stages of endometriosis." (PMID 36835217, 2023). "The role of IL-10 in endometriosis has been studied in an animal model." (PMID 37446108, 2023). "Elevated levels of IL-10 have been identified as a key factor in the development of endometriosis, and localized secretion of IL-10 by plasmacytoid dendritic cells promotes the development of endometriosis through pathologic angiogenesis in the early stages of the disease." (PMID 37941058, 2023). "At the phyla level, a higher abundance of Proteobacteria in peritoneal fluid could be seen among infertile patients with endometriosis, in which several inflammatory factors, including IL-6, IL-10, IL-13, and TNF-α, may be involved." (PMID 37764164, 2023). "The increase of the CD4+/CD8+ T cell ratio and decrease of anti-inflammatory IL-10 could be involved in the pathogenesis of endometriosis and may secondarily affect the functions of monocytes and macrophages." (PMID 35303800, 2022). "We cannot rule out the possibility that, in addition to elevated proinflammatory cytokines, higher levels of anti-inflammatory cytokines (IL-10) in the blood of endometriosis patients may also affect phagocyte functions." (PMID 35888644, 2022). "Our study shows the increase of autophagy of ectopic endometrium may via the high level of IL-10 which secrets by endometriosis related peritoneal macrophages." (PMID 36263059, 2022). "Interestingly, PMs from patients with endometriosis also exhibited elevated levels of IL-10 and IL-16." (PMID 35565370, 2022).
endometriosis (continued). "Interestingly, studies have revealed elevated levels of IL-10 in the peritoneal fluid of women with advanced endometriosis." (PMID 36422544, 2022). "It was reported that the concentration of Th1 cell-related cytokines like interferon-γ (IFN-γ) was lowly expressed, while Th2 cell-related cytokines like interleukins (IL)-4, IL-10, and IL-13 were highly expressed in the serum of the patients with endometriosis." (PMID 34429116, 2021). "In support of these findings, it has been shown that depletion of IL-10 in a surgically induced endometriosis murine model, led to a significant decrease of the endometrial lesions size, while the IL-10 administration promoted the growth of endometrial lesions in this model." (PMID 34639133, 2021). "Women with endometriosis had increased concentrations of IL-6 and IL-10." (PMID 34360900, 2021). "The role of IL‐10‐secreting pDCs in the pathogenesis of endometriosis awaits further investigation." (PMID 31418859, 2019). "However, the role and action of IL‐10 on angiogenesis during the late stage of endometriosis are unclear (‘Role in late stage’)." (PMID 31418859, 2019). "On the other hand, elevated expression of immunosuppressive cytokines in endometriosis has also been reported, like IL-4 and IL-10, which are involved in the development of disease through stimulating survival, growth, invasion, angiogenesis, and immune escape of endometriotic lesions." (PMID 32063886, 2019). "Although pDCs may promote tumour development by creating an immune‐suppressive microenvironment, the integrated role of pDCs and IL‐10 in endometriosis awaits further investigation." (PMID 31418859, 2019). "As previously discussed, various IL‐10‐expressing immune cell types and non‐immune cell types have been observed in endometriotic tissues during this late stage; therefore, additional investigations are needed to clarify the role of IL‐10‐pDCs during the early stage of endometriosis in humans." (PMID 31418859, 2019). "Based on these findings, it is important to clarify whether and how IL‐10‐mediated angiogenesis, as well as immune suppression, contributes to the development of late‐stage endometriosis." (PMID 31418859, 2019). "The anti-inflammatory cytokine IL-10 is also increased in endometriosis." (PMID 28300844, 2017). "Moreover IL-4 and IL-10 were shown to be upregulated in peripheral lymphocytes in women with endometriosis." (PMID 23843796, 2013). "Although DCs do not directly contribute to the pain associated with endometriosis, they may do so indirectly by secreting cytokines that support lesion survival, such as IL-10, and pro-inflammatory cytokines like IL-1β and IL-6, which promote neurogenesis." (PMID 40747182, 2025). "Previous research demonstrated that IL-10 from infiltrated plasmacytoid dendritic cells may suppress immunity against endometrial implants to contribute to the development of endometriosis and promote angiogenesis in the early stage of endometriosis." (PMID 37600687, 2023). "Therefore, Olsenella may be involved in the development of endometriosis by modulating the level of IL-10." (PMID 37600687, 2023). "Endometriosis is known to be associated with a plethora of various proinflammatory and immunoregulatory cytokines, and in the present study we confirmed that the peritoneal fluid of women with this disease contains increased concentrations of TGF-β1/2, IL-6, and IL-10." (PMID 34501240, 2021). "In addition to pDCs, non‐immune cells seem to express IL‐10 in endometriotic lesions; however, whether IL‐10‐expressing non‐immune cells contribute to the pathogenesis of endometriosis awaits further investigation." (PMID 31418859, 2019). "The findings from the in vivo assay are consistent with those observed in vitro and suggest that the IL‐10–IL‐10R pathway may enhance angiogenesis by acting on at least two cell types, endometriotic cells and vessel endothelial cells, in the context of endometriosis." (PMID 31418859, 2019).
endometriosis (continued). "As VEGF is a classic angiogenic factor and its level is significantly elevated in the peritoneal fluid of patients with endometriosis 34, we next examined whether angiogenesis mediated by the IL‐10–IL‐10R pathway was dependent on VEGF secretion from HUVECs or EN‐MSCs." (PMID 31418859, 2019). "Thus, dysregulated local IL‐10 activity may enhance the development of endometriosis during the early stage." (PMID 31418859, 2019). "Nevertheless an increase in IL-10 expression in peritoneum within the pouch of Douglas may lead to supressed immunity within this local area allowing for ectopic endometrial cells to survive and develop into endometriosis lesions." (PMID 25207642, 2014). "In particular, according to these latter authors, increased IL10 production may partially contribute to the disturbed immune regulation in patients with endometriosis, because it attenuates TNF-α-induced IL6 synthesis via NF-kappaB and MAPK pathways in endometriotic cells." (PMID 23843796, 2013). "When they migrate to the site of the ectopic endometrial lesion, they secrete IL-10 and TGF-β, which downregulate the immune response, allowing the endometriosis lesion to escape." (PMID 40747182, 2025). "The interleukin IL-4/IFN-γ, IL-10/IFN-γ, and IL-4/IL-2 ratios are higher in women with endometriosis, probably in the late stage." (PMID 40508002, 2025). "Furthermore, the peritoneal fluid of women with endometriosis displays increased levels of immunosuppressive cytokines, such as IL-10 and IL-12, which may inhibit the activity of activated CD4 + T cells and contribute to immune evasion by endometriotic lesions." (PMID 40313549, 2025). "We investigated the relationship between the endometriosis severity, IL-8, IL-10, BDNF, VEGF-A serum and tissue levels, patient-related pain, and physical activity in a cohort of 46 patients diagnosed with endometriosis who underwent surgery." (PMID 39202309, 2024). "Higher circulating levels of IL-10 have indeed been reported in patients with stage III and IV endometriosis." (PMID 39595086, 2024). "Vaccines using Bacillus Calmette–Guérin (BCG) are among the most effective immunotherapeutic agents that stimulate NK cells and prevent the typical IL6, IL10, and IL4 responses observed in endometriosis." (PMID 38543097, 2024). "The primary objective of this study was to investigate the role of IL-8, IL-10, VEGF-A, and BDNF in assessing and determining endometriosis severity." (PMID 39202309, 2024). "Among anti‐inflammatory cytokines, IL‐4, IL‐10, and transforming growth factor‐beta (TGF‐β) levels are also elevated both in the peripheral blood and in the peritoneal fluid of patients with endometriosis." (PMID 37693240, 2023). "After the analysis, it was detected that the levels of IL-6, IL-10, IL-13, and TNF-α were significantly higher in women with endometriosis and infertility (P < 0.05)." (PMID 38601772, 2023). "Activated naïve T cells produce IL23 and consequently increase production of IL10 and IL17, both of which are factors promoting endometriosis progression." (PMID 35935991, 2022). "Several cytokines are elevated in the peritoneal fluid and in the serum of patients with endometriosis; however, the cytokines IL-1β, TNF-α, IL-6, and IL-10 play a fundamental role in the pathogenesis of endometriosis." (PMID 35807280, 2022). "As can be seen, the concentrations of IL-6, IL-10, and TGF-β1/2 were found to be significantly higher in the peritoneal fluid of endometriosis patients as compared to the control group." (PMID 34501240, 2021). "Higher levels of expressed IL-6 were also measured in the peritoneal fluid and serum from women with endometriosis, along with TGF-β isoforms, IL-1β, IL-10, and IL-17AF." (PMID 33435569, 2021). "On the other hand, it has been reported that the serum levels of IL-8, MCP-1, IL-10, IL-1β and TGF-β are also increased in patients with endometriosis." (PMID 34639133, 2021).